RNU6-1226P (RNA, U6 small nuclear 1226, pseudogene)
Gene: Small nuclear RNA gene on chromosome 6 (112,196,440 to 112,196,546, reverse strand). Ensembl gene ENSG00000207044.
Homologues: Orthologues: chimpanzee U6 (100% identical), macaque U6 (97% identical), dog U6 (75% identical). Paralogues in human: RNU6-41P (86% identical), RNU6-12P (84% identical), RNU6-13P (84% identical), RNU6-15P (84% identical), RNU6-25P (84% identical), RNU6-32P (84% identical), RNU6-44P (84% identical), RNU6-880P (84% identical), RNU6-1 (83% identical), RNU6-1152P (83% identical), RNU6-166P (83% identical), RNU6-17P (83% identical), and 1287 more.